VCAM1 (vascular cell adhesion molecule 1)
Diseases named in the same sentence as VCAM1 in open-access papers (continued):
Sharing a sentence is not in itself a finding about the gene and the disease.
allergic conjunctivitis (1 paper, 2012). "Antihistamines with multiple mechanisms of action can be effective during the early and late phases of allergic conjunctivitis by blocking the interaction between β1 integrins and vascular cell adhesion molecule (VCAM)-1." (PMID 23271999, 2012).
ANCA-associated vasculitis (1 paper, 2025). "To further explore tissue-specific expression patterns, we validated the expression characteristics of the two oxidative stress-related hub genes (VCAM1 and VEGFA) identified from the tubulointerstitial dataset in ANCA-associated vasculitis glomerular tissues (GSE104948 and GSE108109)." (PMID 40369957, 2025).
appendicitis (1 paper, 2024). Acute inflammation of the vermiform appendix. "The mean serum VCAM-1 levels in patients with perforated appendicitis were higher than in those with simple appendicitis (p < 0.001)." (PMID 38928671, 2024). "Pre-surgical serum VCAM-1 was tested in children with acute appendicitis within 72 h of symptoms (from day 1 to day 3)." (PMID 38928671, 2024).
atopic asthma (1 paper, 2019). An asthma that is characterized by symptoms that are triggered by an allergic reaction caused by inhaled allergens such as dust mite allergen, pet dander, pollen and mold. "In addition, VCAM1 was shown to express in endothelial cells of atopic asthma cases, but not COPD cases 65, and present an association with lung function." (PMID 31419078, 2019).
autism (1 paper, 2025). Persistent deficits in social interaction and communication and interaction as well as a markedly restricted repertoire of activity and interest as well as repetitive patterns of behavior. "From the literature, in some cohorts, lower VCAM-1 correlated with higher severity of autism symptoms—especially social and communication difficulties." (PMID 41300606, 2025). "However, they could not find a correlation between the levels of sPECAM-1 and VCAM-1 and clinical variables, including results on the Autism Diagnostic Interview-revised (ADI-R), age, weight, and height." (PMID 41300606, 2025).
B cell Acute Lymphoblastic Leukaemia (1 paper, 2020). "VCAM-1/VLA-4 communication plays a key role in stroma remodelling in numerous B cell malignancies: in B cell Acute Lymphoblastic Leukaemia (ALL), Jacamo and colleagues demonstrated that following VCAM-1/VLA-4 interaction, BMSCs show increased NF-κB signalling activation." (PMID 32098106, 2020).
B-cell acute lymphoblastic leukemia (1 paper, 2021). A neoplasm of lymphoblasts committed to the B-cell lineage, typically composed of small to medium-sized blast cells. "SHP2E76K activation mutation in bone marrow mesenchymal stromal cells (BMSCs) upregulates vascular cell adhesion molecule 1 (VCAM-1) expression by increasing the PI3K/Akt phosphorylation level and further induces BMSC-mediated chemoresistance in B-cell acute lymphoblastic leukemia (B-ALL)." (PMID 33777940, 2021).
B-cell lymphoma (1 paper, 2025). "Top proteins that were consistently associated with B-cell lymphoma across the EPIC, ARIC and UK Biobank cohorts included: CXCL13, sCD23, FCRL1, FCRL3, SEMA7A, CD72, CD48, LY9 and VCAM1." (PMID 40894013, 2025).
babesiosis (1 paper, 2017). Babesiosis refers to a condition caused by microscopic parasites that infect the red blood cells. "Markers for endothelial activation, such as TM and HMGB1, were significantly increased in dogs with complicated babesiosis at admission compared to day 6, while compared to dogs with uncomplicated babesiosis VCAM-1 was increased." (PMID 28363279, 2017). "Concentrations of TM, HMGB-1, VCAM-1 and suPAR were increased in dogs with babesiosis at admission compared to healthy dogs." (PMID 28363279, 2017). "Dogs with complicated babesiosis at admission had higher concentrations of VCAM-1 compared to dogs with uncomplicated babesiosis." (PMID 28363279, 2017). "Markers for endothelial activation, such as TM, HMGB-1 and VCAM-1, were significantly increased in dogs with babesiosis at admission compared to healthy dogs." (PMID 28363279, 2017).
bacteremia (1 paper, 2018). "VCAM-1 was the only mediator that consistently showed significant differences in univariate and multivariate logistic regressions, and with the strongest association with bacteremia." (PMID 29681903, 2018). "Despite this, VCAM-1 stands out as a possible important marker for bacteremia in contrast to results from an earlier study." (PMID 29681903, 2018). "In our study, we found six of the soluble mediators analyzed that differentiated between patients with and without bacteremia: TNF-α, CCL4, TIMP-1, VCAM-1, ICAM-1, and E-selectin." (PMID 29681903, 2018). "Using unsupervised hierarchical clustering, we found that TNFα, CCL4, E-selectin, VCAM-1, ICAM-1, and TIMP-1 could be used to discriminate between patients with and those without bacteremia." (PMID 29681903, 2018).
Bell's palsy (1 paper, 2025). Partial or complete paralysis of the facial muscles of one side of a person's face. "(Genetic correlation between CCL19 and Bell’s palsy: 0.2105, p = 0.042; genetic correlation between VCAM1 and Bell’s palsy: 0.2478, p = 0.017; genetic correlation between OSM and Bell’s palsy: 0.41934, p = 0.021)." (PMID 40299566, 2025). "LDSC identified significant genetic associations between CCL19, VCAM1, OSM, and Bell’s palsy." (PMID 40299566, 2025). "Thus, CCL19, SELL and VCAM-1 may not be sequential activation of a single pathway, but rather synergize through different mechanisms such as chemotaxis, adhesion and barrier modulation to drive the inflammatory response and pathological injury in Bell’s palsy." (PMID 40299566, 2025).
bone marrow failure (1 paper, 2020). "Meanwhile, the proportion of VCAM‐1+ MSCs in patients with bone marrow failure of acquired AA was sharply declined, which collectively confirmed the negative correlation and potential application with AA as well." (PMID 32597552, 2020).
brucellosis (1 paper, 2024). Brucellosis is a bacterial infection that spreads from animals to people via unpasteurized dairy products or by exposure to contaminated animal products or infected animals. "In our study, we observed elevated levels of endothelial injury markers, including von Willebrand factor (VWF), VCAM-1, and ICAM-1, in patients with acute and chronic Brucellosis." (PMID 39872944, 2024).
Cachexia (1 paper, 2025). Severe weight loss, wasting of muscle, loss of appetite, and general debility related to a chronic disease. "Cluster 6 also included marker genes indicative of endothelial inflammation/dysfunction and increased vascular permeability (e.g., Selp, Icam1, Vcam1) which were elevated prior to cachexia development." (PMID 39810606, 2025).
cerebral lesions (1 paper, 2018). "Thus, the lower intensity of cerebral lesions observed in Ext-Ts-treated PbA-infected mice in our investigation was related to the lower IFN-γ and consequently lower ICAM-1 and VCAM-1 expression in the organ as well as the decrease of chemokine receptor CCR5 involved in leukocyte trafficking." (PMID 29367729, 2018).
Chagas cardiomyopathy (1 paper, 2015). A disease of the cardiac muscle developed subsequent to the initial protozoan infection by trypanosoma cruzi. "In Chagas cardiomyopathy, there is an inflammatory vasculopathy, which is demonstrated by sustained expression of the adhesion molecules E-selectin, VCAM-1 and ICAM-1 during T. cruzi infection." (PMID 25978361, 2015).
Chagas disease (1 paper, 2015). A parasitic infection caused by Trypanosoma cruzi. "Endothelial activation during Chagas disease entails the expression of cell adhesion molecules such as E-selectin, vascular cell adhesion molecule-1 (VCAM-1) and intercellular cell adhesion molecule-1 (ICAM-1) through a mechanism involving NF-κB activation." (PMID 25978361, 2015).
chlamydial infection (1 paper, 2008). "VCAM-1 has also been associated with a Th1 immune response and clearance of chlamydial infection." (PMID 18974840, 2008). "ICAM-1 and VCAM-1 have been found to be significantly elevated in the vasculature after genital chlamydial infection in the murine model." (PMID 18974840, 2008).
cholestasis (1 paper, 2021). Impairment of the bile flow caused by obstruction within the liver, or outside the liver in the bile duct system. "Our group has previously defined critical roles for the ADAM17-regulated cytokines TNFα and IL-6, cytokine receptor TNFRI, and immune cell adhesion molecule VCAM-1, in cholestasis associated sickness behavior development in BDL mice." (PMID 35095853, 2021).
chorioamnionitis (1 paper, 2022). A morphologic finding indicating inflammation of the fetal sac membranes. "In-vivo studies confirmed this finding by increasing VCAM-1 on cord blood samples of preterms born from maternal chorioamnionitis." (PMID 35625922, 2022).
choroidal neovascularization (1 paper, 2023). An eye disorder described by the growth of new blood vessels that originate from the choroid through a break in the Bruch membrane into the sub–retinal pigment epithelium (sub-RPE) or subretinal space. "In nAMD, adhesion molecules such as Intercellular Adhesion Molecule 1 (ICAM-1) and Vascular Cell Adhesion Molecule 1 (VCAM-1) have been detected in choroidal neovascularization (CNV) and silencing VCAM-1 mRNA expression could suppress experimental CNV." (PMID 37985993, 2023).
chronic fatigue syndrome (1 paper, 2024). "Instead, post-COVID-19 syndrome (PCS) serum and PCS with chronic fatigue syndrome (CFS) serum led to a significant reduction in surface expression of VCAM-1 and E-selectin compared with healthy control serum samples." (PMID 39066212, 2024).
chronic venous insufficiency (1 paper, 2021). Chronic form of venous insufficiency (disease). "The upregulation of the local expression of VCAM1 is commonly observed in chronic venous insufficiency and venous hypertension." (PMID 34206566, 2021).
Churg-Strauss syndrome (1 paper, 2013). "For future studies, we suggest that human anti-VCAM-1 mAb may exert anti-inflammatory effects in other eosinophilic diseases, such as eosinophilic gastroenteritis, Churg-Strauss syndrome and idiopathic hypereosinophilic syndrome." (PMID 23855490, 2013).
Coats disease (1 paper, 2020). Coats disease (CD) is an idiopathic disorder characterized by retinal telangiectasia with deposition of intraretinal or subretinal exudates, potentially leading to retinal detachment and unilateral blindness. "Of the 22 measured cytokines, the concentrations of 8 cytokines (VEGF, IL-6, IL-8, MCP-1, MIP-1α, IP-10, VCAM-1 and ICAM-1) were significantly higher in the Coats disease group than in the control group (all P < 0.002)." (PMID 32370768, 2020). "The concentrations of 8 cytokines (VEGF, IL-6, IL-8, MCP-1, MIP-1α, IP-10, VCAM-1 and ICAM-1) were significantly higher in the Coats disease group than in the control group (all P < 0.002)." (PMID 32370768, 2020). "In the present study, significantly elevated VCAM-1 and ICAM-1 provide a possible molecular evidence for increased vascular permeability and accumulation of inflammatory cells in Coats disease." (PMID 32370768, 2020). "Various cytokines in the AH, including elevated VEGF, IL-6, IL-8, MCP-1, MIP-1α, IP-10, VCAM-1 and ICAM-1, may be involved in the pathogenesis and progression of Coats disease." (PMID 32370768, 2020).
cocaine addiction (1 paper, 2025). "CALM3 and JUN were downregulated in the cocaine addiction group compared to controls (p < 0.05), whereas CCL2, CD44, CLIC1, and VCAM1 were upregulated (p < 0.05)." (PMID 41465087, 2025).
colonic disease (1 paper, 2025). "An alternative strategy for directly inhibiting VCAM-1-mediated cell trafficking during colonic disease is specific VCAM-1 knockdown by antisense oligonucleotides (ASOs)." (PMID 40095109, 2025). "Though this has somewhat overshadowed the use of immunoblocking antibodies as therapeutic agents for IBD and CRC, studies into anti-VCAM-1 antibody mechanisms and efficacy still provide significant insights into cell adhesion-targeting strategies in colonic diseases." (PMID 40095109, 2025). "Regardless of their decreased use in more recent years, VCAM-1-targeted ASOs could still present a viable drug strategy for the targeted treatment of colonic diseases." (PMID 40095109, 2025).
coronary artery stenosis (1 paper, 2015). "An upregulated VCAM-1 expression is associated with a higher coronary SYNTAX score, indicating severe coronary artery stenosis." (PMID 26622332, 2015).
corticobasal syndrome (1 paper, 2025). Corticobasal syndrome (CBS) is a rare neurodegenerative disease characterized by multifaceted motor system dysfunctions and cognitive defects such as asymmetric rigidity, bradykinesia, limb apraxia, and visuospatial dysfunction. "Neither transferrin nor VCAM-1 has been studied in the context of progressive supranuclear palsy (PSP) or corticobasal syndrome (CBS)." (PMID 41225971, 2025).
craniosynostosis (1 paper, 2011). Craniosynostosis is defined as the premature fusion of one or more cranial sutures leading to secondary distortion of skull shape resulting in skull deformities with a variable presentation. "After controlling for variables contributing to potential bias, FGF7, SFRP4, and VCAM1 emerged as genes associated with single-suture craniosynostosis due to their significantly large changes in gene expression compared to the control population." (PMID 22028906, 2011). "The results from this study not only identified FGF7, SFRP4, and VCAM1 as novel genetic candidates for the cause of single-suture craniosynostosis like, but also confirmed the involvement of ECM-mediated focal adhesion and Ffg/Wnt/Igf signaling pathways that may contribute its pathogenesis." (PMID 22028906, 2011). "Finally, identification of ECM-mediated focal adhesion as a candidate network biomarker also substantiates the identification of VCAM1 and IGFBP2 as potential individual gene biomarkers for craniosynostosis." (PMID 22028906, 2011).
cutaneous leishmaniasis (1 paper, 2018). Leishmaniasis affecting the skin. "CLA-positive cells can use both VLA-4/VCAM-1 and LFA-1/ICAM-1 for extravasation on skin surfaces, which could account the enrichment of T cells expressing this receptor in the lesion of cutaneous leishmaniasis patients." (PMID 30662437, 2018).
cutaneous melanoma (1 paper, 2016). A primary melanoma arising from atypical melanocytes in the skin. "In addition, cell adhesion molecules, including ICAM-1 and VCAM-1, have been implicated in tumor progression in cutaneous melanoma." (PMID 27314329, 2016).
cutaneous squamous cell carcinoma (1 paper, 2016). "Expression of VCAM-1 was found to be highest in poorly differentiated cutaneous squamous cell carcinoma." (PMID 26881177, 2016).
cysticercosis (1 paper, 2024). "However, contrary to initial hypotheses, the coexistence of HIV with cysticercosis did not lead to significant alterations in the levels of TNF-α, IFN-γ, IL-5, and VCAM-1." (PMID 39093864, 2024).
demyelinating disease (1 paper, 2019). A broad group of disorders that affect the myelin sheaths that cover the neurons. "CBD has also been shown to suppress IL-1β production in a mouse viral-induced demyelinating disease model, while reducing vascular activation as determined by monitoring endothelial VCAM-1 expression." (PMID 31681262, 2019).
demyelination (1 paper, 2023). "Furthermore, in a mouse (1-month-old) model of viral-induced demyelination, CBD (5 mg/kg; i.p) attenuated morphological alterations in microglia, and reduced production of IL-1β, chemokines, and vascular cell adhesion molecule-1 (VCAM-1) through adenosine A2A receptors." (PMID 37032821, 2023).
diabetic angiopathy (1 paper, 2013). "The results also provide experimental evidence of diabetic angiopathy, which is generated by ETD through increases in VCAM-1, ICAM-1 and P-selectin." (PMID 24499567, 2013).
erythroleukemia (1 paper, 2017). Acute erythroid leukemia characterised by the presence of at least 50% erythroid precursors and at least 20% myeloblasts in the bone marrow. "To decouple the effects of VLA-4/VCAM-1 interactions from cytokine secretion on gap formation in endothelial monolayers, we performed experiments with K562 human erythroleukemia wild type (WT) cells and K562 cells stably transfected with the α4 integrin (K562 VLA-4)." (PMID 28393886, 2017).
fibrosarcoma (1 paper, 2016). A malignant mesenchymal fibroblastic neoplasm affecting the soft tissue and bone. "In the T241 fibrosarcoma model, there was a high expression of ICAM-1 and VCAM-1 in the tumor vasculature in control mice." (PMID 27385210, 2016).
fungal infection (1 paper, 2020). "Thus, VCAM1/VLA4 interaction mediates Ly6Clow monocyte recruitment to the brain in a TNFR signaling dependent manner during fungal infection." (PMID 32101593, 2020).
H1N1 virus infection (1 paper, 2013). "In our current study, analyses of cellular adhesion molecule expression on A549 in response to H1N1 virus infection revealed an upregulation of ICAM-1, VCAM-1, and E-selectin; this is subsequently inhibited by TSL-1." (PMID 24073006, 2013).
Hashimoto thyroiditis (1 paper, 2025). An autoimmune disorder caused by the production of autoantibodies against thyroid tissue. "Also, Abbasalizad Farhangi and Tajmiri26 reported that consuming 2 g/day N. sativa powder for 8 weeks caused significant decrease in serum VCAM-1 levels, whereas did not significantly alter serum ICAM-1 levels in Hashimoto’s thyroiditis patients compared with the controls." (PMID 40365513, 2025).
hematoma (1 paper, 2024). A hematoma is a collection of blood from a vascular structure into an extravascular space. "On day 1 after ICH, the expression of VCAM‐1, ICAM‐1, and PECAM‐1 were significantly up regulated in the peri‐hematoma region when compared to the sham group." (PMID 38044319, 2024).
hemophilia (1 paper, 2020). Hemophilia is a genetic disorder characterized by spontaneous hemorrhage or prolonged bleeding due to factor VIII or IX deficiency. "A biomarker to evaluate the severity of hemophilia is plasma soluble vascular cell adhesion protein 1 (VCAM-1), which was significantly higher in patients with more severe arthropathy on X-ray." (PMID 33023246, 2020).
hemorrhage (1 paper, 2014). Loss of blood from the vascular compartment to the exterior or into nonvascular body space as a result of rupture or severance of the blood vessels. "In collagenase-induced ICH, enhanced MRI with microparticles of iron oxide targeted to VCAM-1 revealed the maximal VCAM-1 expression 24 h after ICH which returned to baseline 5 days following hemorrhage induction." (PMID 25477782, 2014).
hepatoblastoma (1 paper, 2025). Hepatoblastoma (HB) is a malignant hepatic tumor and is the most common pediatric liver cancer. "Another scRNA-seq study analyzing treatment-naïve hepatoblastoma samples revealed an immune landscape marked by the aberrant accumulation of erythroblastic islands, composed of VCAM1+ macrophages and erythroid cells, which was inversely correlated with patient survival." (PMID 40684183, 2025).
HTLV infection (1 paper, 2012). "Genes highly expressed in both cell lines, like VCAM1 which is implicated in the formation of syncitia during HTLV infection, or the anti-apoptotic protein BIRC3/HIAP-1/CIAP-2 that prevents the death of naturally infected HTLV-1 CD8+ are easily visualized with this representation." (PMID 22911729, 2012).
Huntington disease (1 paper, 2025). Huntington disease (HD) is a rare neurodegenerative disorder of the central nervous system characterized by unwanted choreatic movements, behavioral and psychiatric disturbances and dementia. "VCAM1 is involved in taurine metabolism, xenobiotic detoxification by cytochrome P450, and neurodegenerative disease pathways (e.g., Alzheimer’s and Huntington’s diseases), implying its potential in metabolic detoxification and neuroprotection." (PMID 41465087, 2025).